CD200 (CD200 molecule)
Diseases named in the same sentence as CD200 in open-access papers (continued):
Sharing a sentence is not in itself a finding about the gene and the disease.
cancer (continued). "Therefore, some studies believe that CD200 may have dual effects on different links of different cancers (Nip, Wang & Liu, 2023)." (PMID 40718780, 2025). "Notably, the shedding of the extracellular domain (soluble CD200) from basal cell carcinoma represents a novel mechanism of immune evasion that acts against the efficacy of available T-cell immune blockers used to treat these cancers." (PMID 39795972, 2024). "Furthermore, CD200-targeted immunotherapy may have varying success among patients depending on the type of cancer and their stage of disease progression, as demonstrated by the preliminary results of the samalizumab clinical trial." (PMID 36756156, 2023). "Moreover, CD200 overexpression is correlated with poor prognosis among some of these cancers, suggesting that high levels of CD200 may facilitate tumorigenesis." (PMID 36756156, 2023). "Furthermore, CD200 expression in blood endothelial cells may highlight how the protein’s presence can be strategically induced by certain metastasizing cancers." (PMID 36756156, 2023). "Consequently, it can be inferred that CD200‐positive or CD276‐positive cancer stem cells may orchestrate metastatic latency through immune evasion." (PMID 33932112, 2021). "Wnt, TGF‐β, and Hedgehog signaling, which are recognized as stemness‐related pathways, showed a significant association with the expression of CD200 and CD276, suggesting cancer stem cell–specific immune checkpoints could be downregulated by inhibiting these pathways." (PMID 33932112, 2021). "It has been reported that CD200 blockade may improve the efficacy of cancer immunotherapy." (PMID 34692697, 2021). "Moreover, CD200 expression can also be induced on cancer cells." (PMID 32117298, 2020). "However, CD200 seems to have a dual role in cancer development and metastasis." (PMID 30653571, 2019). "The implementation of the B7H1, B7H4, and CD200 inhibitors to DC cancer vaccines seems to be appropriate, and could make the immune system of a host more sensitive to cancer antigens by means of unblocking the hindering influence of the mentioned molecules on the cytotoxicity of T lymphocytes." (PMID 23632869, 2013). "We focused our research on the CD200/CD200R1 axis, recently pointed out as potential targets in some forms of cancer." (PMID 40904466, 2025). "The last axis with a possible impact on EMS development is CD200/CD200R, engaged also in the pathogenesis of allergies, autoimmune diseases, and cancers." (PMID 38892453, 2024). "Although ample evidence exists linking the CD200/CD200R axis to immunosuppression and cancer progression, current studies have also shown an anti-tumorigenic function associated with this pathway." (PMID 38137547, 2023). "Our findings showed that MLKL was positively correlated with the expression of immune checkpoints such as PD1, PD-L1, PD-L2, and CTLA4 in most cancer types, except for ICOSLG, CD200, CEACAM1, HHLA2, and VTCN1 in BUC." (PMID 37000317, 2023). "The intricate interplay between CD200 and its receptor, CD200R, has prompted extensive research into potential therapeutic strategies for cancer treatment." (PMID 38137547, 2023). "The genes included in the high-expression group were VTCN1, CD200, CD276, and LGALS9, as they showed a higher expression level in all the cancer samples." (PMID 36157232, 2022). "Although CD200 is expressed by less than 4% of BCC cells, which exhibit a cancer stem cell phenotype, MMP11 facilitates high levels of sCD200 secretion into the TME." (PMID 36074574, 2022). "Genes such FAM182A, SOX9, AHNAK2, ENSG00000121031, FLT3LG, PMEPA1, ZFP36L2 in the large intestine, ALB, KRTAP19-1, APOB, CD200, CRYGD, KRTAP24-1, OR6N2 in the liver are novel predictions, and their functions in these cancers can further be studied." (PMID 34997044, 2022). "That also means that cancer stem cells with high TGF‐β, Hedgehog, and Wnt signaling activation are able to display high levels of CD200 and CD276 expression, thus escaping from immunosurveillance." (PMID 33932112, 2021).
cancer (continued). "CD48, CD200 and VISTA are also downregulated in cancer samples, while CD276, LGALS9 and PVR are upregulated in cancer tissue." (PMID 33806327, 2021). "According to gene expression profiles in 33 cancer types, UBE2C were related to many immune markers, such as CD200 which is expressed by various cell types, including B cells, a subset of T cells, and thymocytes." (PMID 34950739, 2021). "Overall, our results suggest that CD200 is an EMT driver and endows cancer stem cell-like features to mouse OSCC cells." (PMID 31627350, 2019). "Much recent success in cancer clinical trials that blocked immune inhibitory signals, predominantly PD-L1, CTLA-4, and CD200 further underscored the importance of these inhibitory signals in reinvigorating the dysfunctional T cell responses." (PMID 29915577, 2018). "Mixed results have also been reported for the Ig superfamily protein CD200 and the transmembrane co-receptor syndecan-4 (SDC4), with both pro- and anti-cancer roles suggested in different situations." (PMID 27144453, 2016). "Our study revealed that there is a significant relationship between the presence and grade of LC, and the expression of CD200 and CD200R molecules on the Mo-DC pulsed with autologous cancer cell lysates." (PMID 23632869, 2013). "This review provides a comprehensive overview of the regulation and therapeutic targeting of immune checkpoint proteins in cancer, covering both classical checkpoints, including PD-1, PD-L1, and CTLA-4, and emerging targets such as LAG-3, TIM-3, TIGIT, BTLA, SIRP-α, CD200, ILT4, and CD24." (PMID 42279386, 2026). "Indeed, the CD200/CD200R signaling pathway plays an etiological role in the survival and metastasis of numerous cancers primarily through suppressive effects on anti-cancer immune surveillance." (PMID 40075669, 2025). "CD200 (also known as OX2), a transmembrane glycoprotein of the immunoglobulin supergene family, is mainly expressed in several types of cancer cells, endothelial cells and activated immune cells, whereas its receptor (CD200R) is mostly expressed in monocytes/myeloid cells and T lymphocytes." (PMID 37313656, 2023). "In pancreatic cancer, CD200 is positively expressed in CAFs and negatively expressed in cancer cells, but no clear correlation is seen with either progression-free survival or overall survival." (PMID 37143134, 2023). "ETS2 was positively correlated with CD200, NRP1, ICOSLG, and TNFSF15 across several cancers." (PMID 36760475, 2023). "To identify potential therapeutic targets of those cancers and immune escape, we have collected more than forty representative immune checkpoint genes, including BTLA, CD200, TNFRSF14, NRP1, LAIR1 and so on, and we evaluated the relationship between expression of COL1A1 and immune checkpoint." (PMID 35789341, 2022). "CD200 (OX-2) and carcinoembryonic antigen-related cell adhesion molecules (CEACAM-1), the cell surface tolerance signals exist commonly between trophoblasts and cancer cells." (PMID 35517798, 2022). "Moreover, our analyses revealed correlations between EMT and immune checkpoints in early-stage LUAD, such as CD200, TNFSF4 and SIRPA, which have also been demonstrated in other types of carcinomas." (PMID 35645555, 2022). "The soluble form of CD200, sCD200, in the serum of CLL patients significantly correlates with severity of the disease and may be concern as a prognostic factor for cancer recurrence." (PMID 33562512, 2021). "Unexpectedly however, the expression levels of most of the analyzed inhibitory immune-checkpoint genes were not different in cancer cells as compared to normal melanocytes, with the exception of CD200 and HVEM, that resulted significantly reduced." (PMID 30653520, 2019). "The CD200/CD200R homeostatic mechanism is of major interest as a target for immunomodulation both to reduce myeloid activity in inflammatory conditions and to block inhibitory signals provided by cancer cells." (PMID 23602662, 2013).
cancer (continued). "CD200 is a membrane glycoprotein belonging to the immunoglobulin superfamily and the over-expression of CD200 has been reported in a number of malignancies, including CLL, as well as on cancer stem cells." (PMID 31803290, 2012). "The challenge is to target CD200-expressing cancer cells without harming healthy tissues." (PMID 39795972, 2024). "Thus, to inhibit cancer progression, strategies to block this CD200 “non-canonical” pathway using sCD200R1 or anti-CD200 monoclonal antibodies may yield favorable outcomes in the clinical setting." (PMID 38137547, 2023). "Exploring the evolutionary advantage of viral CD200 orthologs, the expression and role of CD200 in different biological settings, and previous studies investigating CD200-averse immunotherapy may help us better understand CD200/CD200R’s candidacy as a safe and suitable target for cancer therapy." (PMID 36756156, 2023). "Therefore, the role of CD200 in carcinogenesis and progression of cancer is not unlikely." (PMID 36741370, 2022).
infection (27 papers, 2012 to 2025). The state of being infected such as from the introduction of a foreign agent such as serum, vaccine, antigenic substance or organism. "Percentage body weight loss was calculated from day 0 post-infection, and data suggested that mice treated with CD200-Fc in combination with doxycycline lost less weight than antibiotic control-treated mice, indicating a healthier animal state." (PMID 37199641, 2023). "In this case, the function of CD200/CD200R interaction is to protect the host from “the cytokine storm” produced in response to the infection, which is the principal cause of the deleterious effects seen in CD200 KO mice." (PMID 29607331, 2018). "Collectively these data indicate that the CD200/CD200R lectin-like molecules must play a role in the susceptibility of cells to infection against at least the viral isolates utilized." (PMID 26468886, 2015). "Our results indicate a role of CD200R:CD200 in T cell responses to helminths which has diagnostic and prognostic relevance as a marker of infection for chronic schistosomiasis in mouse and man." (PMID 22496920, 2012). "Notably, CpG sites associated with Il4, Il13, Cd200, and Il1rl1 displayed the lowest methylation levels on Day 1 of infection, followed by an increase over time." (PMID 40170749, 2025). "Interestingly, however, treatment with CD200-Fc of L. major-infected mice caused the parasite to disseminate into a systemic infection similar to that of L. amazonensis." (PMID 27242794, 2016). "To investigate whether MCMV induction of Cd200 transcription required productive replication, we compared expression following macrophage infection with IE3 knockout replication-deficient MCMV (ΔIE3) and replication-sufficient wt MCMV (pSM3fr)." (PMID 25654642, 2015). "CD200-deficient mice demonstrate rapid onset of experimental autoimmune encephalomyelitis and increased susceptibility to acute inflammation induced by bacterial (Neisseria meningitidis) and viral (influenza) infections." (PMID 23012619, 2012). "Consistent with changes in DNA methylation levels, expressions of Il4, Il13, Cd200, and Il1rl1 were highest on the first day of infection and gradually decreased over time." (PMID 40170749, 2025). "Our results suggest that patients with CD200 rs1131199 GG genotype would improve their survival with a strict infection surveillance." (PMID 38455039, 2024). "The effectiveness of CD200-Fc in combination with doxycycline was tested in mice following infection with B. pseudomallei up to 35 days." (PMID 37199641, 2023). "At 6 h post-infection, mice were treated either with CD200-Fc (research grade; R&D Systems) or IgG isotype control (i.n. administration at 1.25 mg/kg of body weight) and monitored for 3 days." (PMID 37199641, 2023). "Flow cytometry analysis revealed that infection of BMDCs with vGH8 resulted in statistically increased expression of CD200 and CD273 on BMDCs’ surface." (PMID 35888991, 2022). "Among the signaling cluster, significantly enhanced expression of Cd200, Camp, Chia1, Ctla2a, Dpep1, Mrc1, and Serpina1b was observed in the wild-type mice on day 7 post-infection." (PMID 34690967, 2021). "CD200-KO mice developed more severe disease and greater lung infiltration, which were completely prevented by depletion of T cells before infection." (PMID 30777093, 2019). "The CD200/CD200R immune-checkpoint pathway has been widely demonstrated to maintain immune homeostasis during infection by preventing excessive activation of macrophages." (PMID 30717437, 2019). "Expression of CD200 on DCs infected with LdCen−/− addback is restored to the levels as observed in LdWT infection thereby indicating that the altered expression of CD200 is tied to the attenuation of virulence in LdCen−/−." (PMID 29915577, 2018). "To further assess the expression of CD200 at earlier time points in vivo and to select bonafide-infected cells, we performed mouse infection experiments with fluorescent Leishmania parasites." (PMID 29915577, 2018).
infection (continued). "In vivo blocking significantly (p = 0.0027) reduced parasite burden 4 weeks post infection in α-CD200 antibody-treated animals as compared to naïve infected that further confirmed the protective capabilities of CD200 blocking." (PMID 29915577, 2018). "Flow cytometric analysis showed that 24 h post infection, CD11c+ splenic DCs showed a strong induction of CD200 in LdWT and a reduced CD200 expression in LdCen−/−." (PMID 29915577, 2018). "To measure the impact of blocking CD200 on CD200R expression, we injected CD200 blocking antibodies or an isotype control on days 0, 3, 6, 9, and 12 following infection with LdWT parasites." (PMID 29915577, 2018). "Our results showed that LdCen−/− infection resulted in consistently reduced CD200 expression compared to LdWT infection in BMDCs, splenic DCs in vitro and in vivo." (PMID 29915577, 2018). "Consistent with the in vitro data, immunization with LdCen−/− parasites induced significantly less CD200 expression on the DCs compared to LdWT infection at both 24 h (p = 0.0069) and 72 h (p = 0.014)." (PMID 29915577, 2018). "To analyze if reduction of CD200 expression is transient or sustained over time in LdCen−/− infection in vivo, we examined splenic CD11c+ DCs at days 7 and 14 in LdWT and LdCen−/−-infected animals." (PMID 29915577, 2018). "Compared to LdWT infection, the percentage of CD200+ DCs and CD200R+ CD4 T cells was found significantly less in LdCen−/−-immunized animals." (PMID 29915577, 2018). "It has been identified that infections by this parasite induce increased expression of CD200 at the protein and mRNA level compared to uninfected macrophages." (PMID 29607331, 2018). "Induction of CD200 upon infection was essential for the parasite virulence and development of systemic Leishmaniasis." (PMID 27242794, 2016). "L. amazonensis has evolved to utilize CD200 expression as a mechanism for inhibiting both NO production and induction of iNOS during infection." (PMID 27242794, 2016). "In accordance with CD200 expression by CD31+ cells, MHC II+ cells were also observed surrounding CD31+ vessels, suggesting that tissue-resident MHC II+ SG-APC interactions with CD200-bearing endothelial cells restricts infection-induced cellular proliferation." (PMID 25654642, 2015). "The Rhesus rhadinovirus (RRV) R15 ORF exhibits 30% homology to human CD200 and is detected in the cytoplasm and on the cell surface during infection." (PMID 23012619, 2012). "At week 8 post-infection, we analysed CD200 and CD200R expression in T cells from the mesenteric LN (MesLN) together with CD44 to distinguish Ag-primed (CD44hi) from naïve (CD44lo) cells." (PMID 22496920, 2012). "The negative regulator, CD200 receptor, and its ligand, CD200, have been shown to regulate macrophage activation and reduce pathology following infection." (PMID 22496920, 2012). "BALB/c mice were challenged with 50 CFU (12.5 50% lethal dose [LD50]) B. pseudomallei (K96243) via the aerosol route (using the Biaera aerosol management platform) and treated at 1 day post-infection with CD200-Fc or IgG control via the intraperitoneal (i.p.)route." (PMID 37199641, 2023). "Interestingly, we have shown that when CD200-Fc is combined with a different class of antibiotic, co-trimoxazole, we do see a consistent reduction in liver infection at day 3 post-infection, which is statistically significant." (PMID 37199641, 2023). "By doing this, CD200 can regulate the airway immunological response against infections." (PMID 35892656, 2022). "This suggested that CD200 has a iNOS regulating role during infection." (PMID 33776999, 2021). "Subdued induction of CD200 by LdCen−/− compared to LdWT infection suggested that blocking this signaling could divert more CD4+ T cells to acquire multi-functionality." (PMID 29915577, 2018). "Furthermore, infection with an addback mutant of LdCen−/− re-expressing centrin induced a higher level of CD200 compared to LdCen−/− infection." (PMID 29915577, 2018).